NLRP3 (NLR family pyrin domain containing 3)
Diseases named in the same sentence as NLRP3 in open-access papers (continued):
Sharing a sentence is not in itself a finding about the gene and the disease.
Cerebral ischemia (continued). "Western blotting revealed that, in comparison with Sham group, the expression of the main components of NLRP3 inflammasome, NLRP3, ASC, and cleaved caspase-1 were enhanced by cerebral ischemia-reperfusion injury." (PMID 37650573, 2023). "Another recent research also reveals that in cerebral ischemia/reperfusion, TET2 demethylated LncRNA TUG1, then subsequently promoted NLRP3 inflammasome and contributed to the inflammatory response." (PMID 36527131, 2022). "The protein expression of NLRP3, ASC, and CASP1 were significantly increased after cerebral ischemia (p < 0.01)." (PMID 36091745, 2022). "Several studies have revealed the beneficial effects of resveratrol in the treatment of AD, cerebral ischemia, and SAH, all of which are closely related to the modulation of NLRP3 inflammasome." (PMID 36160384, 2022). "To further assess the influence of cerebral ischemia on the activation of TAK1 and the inflammasomes NLRP3, NLRC4, and AIM2, we first compared the protein expression of TAK1 and its phosphorylation (pTAK1) in mice after tMCAo or sham surgery." (PMID 34628598, 2022). "In conclusion, in its acute phase, cerebral ischemia not only leads to increased expression but also to enhanced activation of TAK1 and the inflammasome complexes of NLRP3, NLRC4, and AIM2." (PMID 34628598, 2022). "The expression of NLRP3 inflammasome was increased in the in vitro neuronal OGD model and the vector mouse cerebral ischemia model." (PMID 34526897, 2021). "Studies showed that ECM receptors (such as integrins and dystroglycan) NLRP3 and PPAR, which are expressed in the brain microvasculature, mediate the connections between endothelial cells and matrix components in response to cerebral ischemia/reperfusion." (PMID 34512266, 2021). "Nrf2 is reported to inhibit the NLRP3 inflammasome by regulating the TRX/TXNIP complex and consequently hampers cerebral ischemia reperfusion injury." (PMID 33567593, 2021). "miR-29a in astrocyte-derived extracellular vesicles inhibits cerebral ischemia-reperfusion injury through TP53INP1 and NF-κB/NLRP3." (PMID 34220338, 2021). "Studies have shown that in cerebral ischemia, NOD-like receptor family pyrin domain containing 3 (NLRP3) inflammasome is a key mediator in mediating inflammatory responses and results in activation of apoptosis signaling pathways." (PMID 32153398, 2020). "We using NLRP3 shRNA or QNDP found that QNDP or QNDP and sh-NLRP3 obviously inhibited the levels of NLRP3, ASC and cleaved-caspase 1, then to regulate the inflammatory cytokines and inhibit apoptosis in cerebral ischemia in vivo and in vitro." (PMID 32153398, 2020). "Studies have reported NLRP3 inflammasome activation in microglia and neurons after oxygen–glucose deprivation (OGD)/reperfusion in vitro and in cerebral ischemia/reperfusion." (PMID 32195267, 2020). "NLRP3 inflammasome, involved in the regulation of inflammatory cascade, can simultaneously lead to GSDMD-executed pyroptosis in cerebral ischemia." (PMID 33153475, 2020). "The most investigated inflammasome is NLRP3 (NACHT, LRR, and PYD domains containing protein 3 or cryopyrin), which was also reported to be a key player in maintaining neuroinflammation after cerebral ischemia in rodents." (PMID 32645874, 2020). "In summary, brain ischemia leads to the release of extrasynaptic glutamate that induces ER stress and TXNIP/NLRP3 activation." (PMID 32650482, 2020). "Indeed, no matter whether the target is upstream or downstream in the NLRP3 inflammasome pathway at the molecular level, modulating the expression, assembly, activation and secretion of the NLRP3 inflammasome and IL-1β exerts a protective effect on cerebral ischemia-reperfusion injury." (PMID 31747940, 2019). "QKL relieved cerebral ischemia reperfusion injury and suppressed the inflammatory response by inhibiting AMPK-mediated activation of the NLRP3 inflammasome." (PMID 31747940, 2019).
Cerebral ischemia (continued). "In conclusion, this study elucidated that QKL relieved cerebral ischemia reperfusion injury and suppressed inflammatory response, at least in part, by inhibiting AMPK-mediated the activation of NLRP3 inflammasome." (PMID 31747940, 2019). "Additionally, miR-29a-3p in astrocyte-derived extracellular vesicles has been found to mitigate cerebral ischemia-reperfusion injury by downregulating TP53INP1 and the NF-κB/NLRP3 signaling pathway." (PMID 40529227, 2025). "Salidroside may also inhibit the activation of NLRP3 inflammasome and TLR4/NF-κB signaling pathway in rat cerebral ischemia-reperfusion injury by increasing the expression of miR-370-3p." (PMID 38601463, 2024). "In a model of cerebral ischemia/reperfusion injury, PHLDA1 blockade ameliorated the acute brain injury by switching microglia M1/M2 polarization via inhibiting nod-like receptor pyrin domain-containing protein 3 (NLRP3) inflammasome signaling." (PMID 36875102, 2023). "Moreover, as a regulator of the ubiquitination and activity of NLRP3, BRCC3 was activated following cerebral ischemia and TENS treatment reversed the promoted BRCC3 levels induced by ischemic condition." (PMID 37101593, 2023). "Concurrently, the anti-inflammatory property of CEP enables its use in the treatment of cerebral ischemia/reperfusion injury, wherein CEP inhibits NLRP3 signaling, and caspase-1, thereby suppressing the overproduction of IL-1β and IL-18, thus attenuating cerebral ischemia/reperfusion injury." (PMID 36677811, 2023). "Another alkaloid, ephedrine, derived from plants of the Ephedra genus, was demonstrated to attenuate cerebral ischemia injury in the middle cerebral artery occlusion rat model and BV2 microglial cells via Akt/GSK3β/Nrf2 pathway regulation and NLRP3 suppression." (PMID 35418995, 2022). "The results illustrated that the NLRP3 inflammasome was activated in the ischemic penumbra in the cerebral ischemia-reperfusion group but not in the sham group." (PMID 34367186, 2021). "Considering increased amounts of LPA in human ischemic patients and animal models of cerebral ischemia, LPA signaling may regulate NLRP3 inflammasome activation in injured brain following ischemic challenge." (PMID 33202644, 2020). "It has previously been observed that in response to cerebral ischemia, NOD-like receptor family pyrin domain containing 3 (NLRP3) inflammasome may be a key mediator in mediating inflammatory responses and result in activation of apoptosis signaling pathways." (PMID 32153398, 2020). "In the present study, we hypothesized that QKL could ameliorate cerebral ischemia-reperfusion injury and modulate the AMPK/NLRP3 inflammasome signalling pathway." (PMID 31747940, 2019). "Notably: the beneficial effects of Nef on cerebral microvascular endothelial against brain ischemia injury was first elucidated in our study: and first revealed that promoting PGC-1α expression could inhibit BMECs pyroptosis via PGC-1α/NLRP3/GSDMD pathway." (PMID 38910141, 2024). "Our results showed that inhibiting HIF-1α/NLRP3 signaling resolved the MDA/SOD imbalance after thalamic hemorrhagic stroke, which was corroborated by previous studies showing that HIF-1α and NLRP3 inflammasome activation increases brain oxidative stress after cerebral ischemia in rats." (PMID 36944982, 2023). "In addition, the inhibition of the NLRP3 inflammasome decreased the amount of damage after cerebral ischemia, but there was no additional benefit if P2X7 was also blocked." (PMID 36224611, 2022). "However, the possible impact of Tet on the NLRP3 pathway in mice with cerebral ischemia has not yet been reported." (PMID 32419986, 2020). "In summary, apart from mTOR, AMPK and NLRP3, other signals, such as Sphk1, DJ-1, LRRK2 could modulate autophagy to participate in microglia polarization as well as inflammatory mediators’ production, thus affecting neuroinflammatory processes in cerebral ischemia, AD, TBI and other CNS diseases." (PMID 37548945, 2024).
Cerebral ischemia (continued). "However, direct molecular evidence is lacking regarding how quercetin precisely regulates the NLRP3/Caspase-1/GSDMD core pyroptosis axis in microglia in cerebral ischemia models and whether it can directly target NLRP3 to inhibit this axis, thereby alleviating cerebral ischemic injury." (PMID 41892344, 2026). "The pathogenetic mechanism by which NLRP2 could impact the pathogenesis of cerebral ischemia may be similar to that of other members of the family of inflammasomes such as NLRP1 and NLRP3, but is not yet fully defined." (PMID 36297283, 2022).
endothelial dysfunction (170 papers, 2013 to 2026). In vascular diseases, endothelial dysfunction is a systemic pathological state of the endothelium (the inner lining of blood vessels) and can be broadly defined as an imbalance between vasodilating and vasoconstricting substances produced by (or acting on) the endothelium. "NLRP3 inflammasomes are transient large protein aggregates involved in the regulation of the innate immune response but are also associated with endothelial dysfunction during vascular inflammation." (PMID 41439981, 2025). "Nevertheless, NLRP3 inhibition is significant, as its chronic activation has been directly linked to endothelial dysfunction and plaque rupture." (PMID 41303649, 2025). "Beyond its role in uterine and placental inflammation, the NLRP3 inflammasome has also been implicated in other pathophysiological processes related to PE, such as renal injury, endothelial dysfunction, and hypertension." (PMID 40867825, 2025). "Other reviews confirmed that excessive SiO2 exposure can trigger macrophage activation, NLRP3 inflammasome signaling, oxidative stress, and endothelial dysfunction, potentially enhancing cardiovascular risk." (PMID 41470901, 2025). "Previous studies showed that Enterobacteriaceae-derived TMAO can activate the NLR family pyrin domain containing 3 (NLRP3) inflammasome in carotid endothelial cells, leading to endothelial dysfunction and its association with hypertension." (PMID 40624679, 2025). "Concurrently, systemic inflammation, evidenced by NLRP3 overexpression and elevated levels of IL-6, sCD40-L, and C-reactive protein, was associated with endothelial dysfunction biomarkers and increased in post-COVID patients with impaired gas exchange." (PMID 38867241, 2024). "Researchers have suggested that the NLRP3 inflammasome contributes to endothelial dysfunction and causes vascular injury." (PMID 37480029, 2023). "Upon leukocyte activation, endothelial dysfunction and other common pathogenic mechanisms, NLRP3 inflammasome activation, and IL-1β production are promoted in individuals with risk factors for CVDs." (PMID 37680887, 2023). "NLRP3 inflammasomes, an essential element of the innate immune response, are present in the progression of endothelial dysfunction associated with chronic kidney disease (CKD)." (PMID 35719709, 2022). "Recent studies have indicated that endothelial dysfunction and consequent vascular injury and inflammation are associated with the formation and activation of NLRP3 inflammasome." (PMID 36252682, 2022). "Although NLRP3 inflammasome activation is known to be associated with the pathogeneses of metabolic diseases, its pathogenetic roles in CDVs and endothelial dysfunction are incompletely understood." (PMID 35340217, 2022). "Since endothelial senescence is closely linked to endothelial dysfunction, we first explored the impact of the IL-1β-NLRP3 inflammasome loop on endothelium-dependent vascular reactivity." (PMID 35111374, 2022). "Our previous studies clarified that H2S improved hypertension-associated endothelial dysfunction or attenuated lipopolysaccharide-induced acute kidney injury by inhibiting NLRP3 inflammasome." (PMID 35910846, 2022). "Hyperglycemia-associated endothelial dysfunction and atherosclerotic lesions are related to the NLRP3 inflammasome in type 2 diabetes mellitus." (PMID 35874841, 2022). "The TXNIP activates the NLRP3 inflammasome, and thus the ROS-TXNIP-NLRP3 pathway mediates inflammation and causes endothelial dysfunction." (PMID 34266474, 2021). "Metformin or other compounds are also used to lower TXNIP aortic levels in vivo or endothelial levels in vitro in order to restrain NLRP3 activation and protect from endothelial dysfunction and cardiovascular risk factors." (PMID 33567593, 2021). "In this review, we provided a comprehensive perspective on the pivotal role of NLRP3 inflammasome activation in aggravating oxidative stress and endothelial dysfunction and the possible underlying mechanisms." (PMID 32948742, 2020).
endothelial dysfunction (continued). "Induction of cold-inducible RNA-binding protein by irradiation causes endothelial dysfunction via activating NLRP3 inflammasome." (PMID 32226786, 2020). "The underlying mechanisms by which 13-MB improves endothelial dysfunction were shown to involve cytoprotection, inhibition of NLRP3 inflammasome activation and enhanced autophagy." (PMID 31993073, 2020). "Previous work from our group has also explored the role of TMAO associated endothelial dysfunction via NLRP3 inflammasomes, suggesting the important role of TMAO in CVD progression." (PMID 31336567, 2019). "In summary, mDNA contributes to endothelial dysfunction in type 1 diabetes, which is linked to increased inflammatory mediators via activation of the NLRP3 inflammasome in endothelial cells." (PMID 32009974, 2019). "To investigate whether NLRP3 inflammasome is associated with the activation of caspase-1 and endothelial dysfunction in rickettsial infection, we determined the effect of the selective NLRP3 inhibitor MCC950 on the expression levels of active caspase-1." (PMID 39679710, 2025). "In addition, PCSK9 enhances the activity of NLRP3 Inflammasomes by activating this pathway, creating a positive feedback loop that exacerbates myocardial fibrosis and sepsis-associated endothelial dysfunction." (PMID 41008547, 2025). "TMAO activated NLRP3 inflammasomes, causing endothelial dysfunction." (PMID 35448889, 2022). "Moreover, they highlighted the significance of the NLRP3 inflammasome in endothelial dysfunction-associated inflammatory diseases." (PMID 36092165, 2022). "In addition, metformin and many other compounds were used to lower aortic TXNIP levels in vivo or endothelial levels in vitro to block NLRP3 inflammasome activation and protect from endothelial dysfunction and cardiovascular risk factors." (PMID 36252682, 2022). "Besides, the in vivo infusion of IL-1β to mice results in enhanced vascular NLRP3 expression, endothelial dysfunction, and a loss of vasodilatory capacity, which can also be prevented by MCC950." (PMID 35204152, 2022). "NLRP3 makes a fundamental contribution to generating inflammatory responses through secreting a series of pro-inflammatory cytokines that might cause endothelial dysfunction, leukocyte infiltration, and, ultimately, hepatocellular damage during I/R." (PMID 34221267, 2021). "Furthermore, we highlighted the contribution of noncoding RNAs to NLRP3 inflammasome activation-associated endothelial dysfunction, and outlined potential clinical drugs targeting NLRP3 inflammasome involved in endothelial dysfunction." (PMID 32948742, 2020). "Therefore, this study investigated the functional role of NLRP3 inflammasome, and related signaling pathways, in the development of type 1 diabetes-associated endothelial dysfunction." (PMID 32009974, 2019). "NLRP3 activation and ER stress induces placental release of pregnancy-incompatible factors including sFlt-1, IL1β, and other pro-inflammatory cytokines and alarmins into maternal circulation causing oxidative stress, systemic inflammation, and endothelial dysfunction." (PMID 37292200, 2023). "Besides, NLRP3-mediated pyroptosis has been reported in endothelial cells, as a response to elevated ROS induced by hyperhomocysteinemia, and this process shall be a hallmark of endothelial dysfunction within the atherosclerotic plaque." (PMID 35204152, 2022). "We tested the hypotheses that mDNA promotes NLRP3 activation in endothelial cells contributing to endothelial dysfunction and that the genetic deficiency of NLRP3 receptor attenuates vascular dysfunction and inflammatory response observed in streptozotocin-induced type 1 diabetes." (PMID 32009974, 2019). "P. g-OMVs have been demonstrated to induce cellular inflammation, increase levels of reactive oxygen species (ROS), provoke mitochondrial dysfunction, activate the NLRP3 inflammasome, and initiate both cell death and endothelial dysfunction." (PMID 40256625, 2025).